PADI2 (peptidyl arginine deiminase 2)
Diseases named in the same sentence as PADI2 in open-access papers (continued):
Sharing a sentence is not in itself a finding about the gene and the disease.
colon cancer (19 papers, 2017 to 2023). "It has been reported that down-regulation of PADI2 was noted in colon tumors and associated with poor prognosis." (PMID 37627159, 2023). "Colon cancer has, on the other hand, been associated with downregulation of PADI2, while PADI2 affects differentiation of normal colon and can suppress proliferation of colonic epithelial cells through protein deimination, accompanied by arrest of cell cycle progression in G1 phase." (PMID 28587234, 2017). "PADI2 can also inhibit the proliferation of colon cancer cells by inducing G1 phase arrest in colon cancer cells through its citrullination effect." (PMID 37020554, 2023). "Whereas axitinib targeted the ubiquitin ligase SHPRH to increase ubiquitination and proteasome-mediated degradation of β-catenin, nitazoxanide targeted PADI2 to increase citrullination and degradation of β-catenin in colon cancer cells." (PMID 34440153, 2021). "The expression of PADI2 gene in colon cancer has been shown to be down-regulated and PADI2 inhibits the proliferation of colon cancer cells." (PMID 32951601, 2020). "PADI2 expression patterns in colon cancer also appear to differ between the two study groups." (PMID 35218410, 2022). "Likewise, PADI2 is required to inhibit cellular proliferation of colon cancer cells by arresting the G1 phase of the cell cycle." (PMID 32079300, 2020). "In addition, it has been found that PADI2 can arrest the cell cycle in the G1 phase and inhibit the proliferation of colonic epithelial cells by catalyzing the citrullination, which may serve as a target for colon cancer treatment." (PMID 37777749, 2023). "In colon cancer patients, the anti-parasitic drug nitazoxanide (NTZ) targets PADI2 to stabilize PADI2, which increases the citrullination of β-catenin protein in cancer cells and blocks the Wnt/β-catenin signaling pathway, thereby inhibiting the growth of cancer cells." (PMID 37777749, 2023). "Recent report shows that PADI2 overexpression suppresses the proliferation of HCT116 colon cancer cell line and PADI2 is downregulated in colon cancer compared with matching normal tissue." (PMID 35218410, 2022).
Arthritis (15 papers, 2012 to 2024). Inflammation of a joint. "In arthritis, the genetic variation of PADI2 and PADI4 can confer RA susceptibility, and they can aggravate arthritis by promoting the secretion of NETosis and inflammatory cytokines." (PMID 37020554, 2023). "Some of these genes have been previously implicated inautoimmune disease: PADI2 expression has been demonstrated to correlatewith arthritis severity in mice (Johnsen etal., 2011), LGALS1 damages cartilage via inflammationin osteoarthritis and PLCL2 has been associated with systemic sclerosis." (PMID 29360927, 2018). "In summary, the current study shows that PADI2 and PADI4 of the PADI family play a role in promoting arthritis, but whether other members of the PADI family are associated with arthritis remains to be elucidated." (PMID 37020554, 2023). "In order to confirm the effect of PgPAD on the progression of arthritis, the internal PAD (PADI2 and PADI4) production in mouse joint tissue was determined." (PMID 33076980, 2020).
prostate carcinoma (14 papers, 2020 to 2025). A carcinoma that arises from epithelial cells of the prostate gland. "Clinical studies have shown that PADI2 overexpression was correlated with cancer progression and poor prognosis, e.g., in ovarian or prostate cancer." (PMID 37627159, 2023). "Compared to normal tissue, PADI2 protein is increased in breast, cervical, colon, liver, lung, ovarian serous, thyroid, and prostate cancers." (PMID 32248654, 2020). "PADI2 promotes protein stability and transcriptional activation of AR in prostate cancer cell line." (PMID 37228649, 2023). "PADI2 is H3 arginine demethylase, a key mediator for AR in prostate cancer progression." (PMID 37228649, 2023). "PADI2 gene expression is required for cell-cycle progression of prostate cancer cells and for proliferation of CRPC prostate cancer cells both in vitro or in vivo." (PMID 32079300, 2020).
colorectal cancer (12 papers, 2017 to 2025). A primary or metastatic malignant neoplasm that affects the colon or rectum. "Cantarino and colleagues found that down-regulation of PADI2 is an early event in the pathogenesis of colorectal cancer and is associated with poor prognosis." (PMID 30740359, 2019). "Furthermore, four genes, ABCG2, PADI2, CA7, and TGFBI, have been verified in previous studies as potentially correlated with colorectal cancer." (PMID 28229027, 2017).
Alzheimer disease (10 papers, 2019 to 2024). A progressive, neurodegenerative disease characterized by loss of function and death of nerve cells in several areas of the brain leading to loss of cognitive function such as memory and language. "Studies have indicated that the aberrant activation of PADI2, a gene expressed throughout the nervous system, is likely associated with the development of neuropsychiatric diseases characterized by neurodegenerative processes, such as Alzheimer's disease and multiple sclerosis." (PMID 38788487, 2024). "PADI2 is found critical in the pathogenesis of neurodegenerative diseases in humans, such as multiple sclerosis (MS) and Alzheimer’s disease (AD)." (PMID 35236296, 2022). "Moreover, PADI2 specifically citrullinates glial fibrillary acidic protein (GFAP), an astrocyte-specific marker protein found in Alzheimer’s disease (AD) patients." (PMID 32079300, 2020). "Interestingly, several transcriptome-wide significant and colocalized genes outside genome-wide significant GWAS loci point to biologically relevant pathways related to neurodevelopment and neurodegeneration (PICALM, a known Alzheimer disease gene, CAMSAP2, AGTPBP1, SETD1A, EPRS, PADI2 and PSAP)." (PMID 38811690, 2024).
multiple sclerosis (10 papers, 2017 to 2025). A progressive autoimmune disorder affecting the central nervous system resulting in demyelination. "Dysregulated PADI2 activity has been implicated in several neurodegenerative diseases, including multiple sclerosis." (PMID 38789799, 2024). "For instance, in multiple sclerosis, the promoter of PAD2(peptidyl arginine deiminase 2) is methylated at only one-third of the level found in normal tissue." (PMID 40533455, 2025).
autoimmune disease (8 papers, 2013 to 2025). A disorder resulting from loss of function or tissue destruction of an organ or multiple organs, arising from humoral or cellular immune responses of the individual to their own tissue constituents. "PADI2 is widely expressed in various tissues and has been shown to trigger citrullinated antigens causing symptoms in autoimmune diseases." (PMID 37627159, 2023).
gastric cancer (8 papers, 2016 to 2023). A primary or metastatic malignant neoplasm involving the stomach. "The case–control analysis showed a significant difference in allele frequency and genotype frequency for rs2746533 in PADI2 between gastric carcinoma patients and controls." (PMID 27478411, 2016). "Since PADI2 or PADI4 catalyzes the conversion of arginine to citrulline in humans, we examined the protein levels of PADI2, PADI4, and H3R26Cit in several human gastric cancer cell lines." (PMID 31058095, 2019).
periodontitis (7 papers, 2018 to 2026). An acute or chronic inflammatory process that affects the tissues that surround and support the teeth. "In the present study, the association of PADI4 and PADI2 SNPs with RA in individuals with self-reported periodontitis was investigated." (PMID 36076933, 2022). "Carriers of the alleles for SNPs rs2057094, rs2076616, and rs2235912 in the PADI2 gene may have an increased risk of developing RA in patients with periodontitis." (PMID 39811802, 2025). "In subjects with periodontitis, carriage of the minor alleles of rs2057094 and rs2235912 in PADI2 significantly increased the risk of RA (odds ratios 1.42 [p = 0.03] and 1.48 [p = 0.02], respectively), and this effect was driven by the anti-CCP-negative RA patients." (PMID 36076933, 2022). "In periodontitis, increased expression of PADI2, PADI4, and citrullinated proteins accompanies the exacerbation of periodontitis." (PMID 37020554, 2023). "The role of PADI polymorphism in periodontitis is not clear, but none of the PADI2 or PADI4 SNPs examined in this study associated with periodontitis." (PMID 36076933, 2022). "Having previously established that PADI4 SNPs associate with RA in the same cohort, we examined whether SNPs in either PADI2 or PADI4 associated with periodontitis in the non-RA control group." (PMID 36076933, 2022). "Nevertheless, the fact that three of four examined PADI2 SNPs in low to moderate linkage disequilibrium (LD) (r2 0.22–0.66) showed significant associations with RA, in general, and with anti-CCP-negative RA, in particular, in patients with periodontitis, supports the validity of our findings." (PMID 36076933, 2022). "None of the examined SNPs in PADI2 (rs2057094, rs2076616, rs2235912 and rs1005753) or PADI4 (rs74058715, rs11203367, rs1748033 and rs2240335) were significantly associated with periodontitis per se (data not shown)." (PMID 36076933, 2022). "Similarly, the mRNA levels of PADI2 and PADI4 were also increased in the gingival tissue of patients with periodontitis compared to healthy controls." (PMID 30064459, 2018). "Similarly to the protein expression of PAD2 and PAD4, the mRNA expression of PADI2 and PADI4, assessed by qPCR analysis, was also significantly higher (p < 0.05 and p < 0.01, respectively) in the gingival tissue of patients with periodontitis compared to healthy controls without periodontitis." (PMID 30064459, 2018).
endometrial cancer (6 papers, 2021 to 2024). Primary or metastatic malignant neoplasm involving the endometrium (mucous membrane that lines the endometrial cavity). "Another studies also show that PADI2 expression is positively associated with the progression of endometrial carcinoma and ovarian cancer and the downregulating PADI2 suppressed the proliferation of these cancer cell lines." (PMID 35218410, 2022). "A previous study has shown that the PAD family member PADI2 played a critical role in the malignancy of endometrial cancer by activating the expression of p-ERK in endometrial cancer cells." (PMID 38474453, 2024). "In endometrial cancer, IGF2BP1 is a direct downstream target of peptidylarginine deiminase II (PADI2) that is required for endometrial cancer progression, and IGF2BP1 binds to the m6A sites of oncogenic SOX2 and prevents its mRNA degradation." (PMID 35541906, 2022). "To further study the role of PADI2 in endometrial carcinogenesis, we generated PADI2‐depleted human endometrial cancer Ishikawa (ISI) cells using a lentiviral approach." (PMID 33747724, 2021). "Peptidylarginine deiminase II (PADI2) is highly expressed in endometrial cancer (EC) and promotes its progression." (PMID 33747724, 2021). "To analyze the molecular mechanisms by which PADI2 induces endometrial carcinoma cell progression, we conducted RNA sequencing (RNA‐seq) in PADI2 knockdown and control ISI cells." (PMID 33747724, 2021). "We also evaluated the effect of PADI2 knockdown on cell proliferation, migration, invasion, and spheroid growth in another endometrial carcinoma cell line, ECC‐1." (PMID 33747724, 2021). "These analyses indicated that IGF2BP1 may be the top candidate target for PADI2 in endometrial carcinoma cells." (PMID 33747724, 2021). "In addition, it has been reported that IGF2BP1 is involved in the guanylation of arginine in endometrial cancer, and the PADI2/MEK1/ERK signalling pathway-mediated dysregulation of IGF2BP1 leads to the upregulation of SOX2 expression, resulting in the malignancy of endometrial cancer cells." (PMID 36894952, 2023). "In addition, a research article by the Zhang laboratory builds on their previously identified mechanism of PADI2-mediated MEK1 citrullination and downstream signalling in endometrial cancer." (PMID 37778381, 2023). "However, a role for PADI2 in endometrial cancer (EC) has not been previously explored." (PMID 33747724, 2021).
interstitial lung disease (6 papers, 2018 to 2025). A diverse group of lung diseases that affect the lung parenchyma. "Studies have shown that the upregulation of PADI2 and citrullination of the protein are associated with RA-related interstitial lung disease (RA-ILD), but the specific mechanism still needs further study." (PMID 37020554, 2023). "We aimed to identify single nucleotide variants (SNV) in PADI2 and PADI4 genes (PAD2 and PAD4 proteins, respectively) associated with susceptibility to interstitial lung disease (ILD) in RA patients and the PAD2 and PAD4 levels." (PMID 37759458, 2023).
skin neoplasm (6 papers, 2017 to 2023). A benign or malignant tumor involving the skin. "Additionally, overexpression of PADI2 in a transgenic mouse model caused the development of spontaneous skin neoplasms." (PMID 32248654, 2020). "Overexpression of PADI2 in transgenic mice promotes the development of skin tumors by enhancing the inflammatory response in the tumor microenvironment." (PMID 32951601, 2020). "In addition to tumorigenesis, PADI2 is believed to promote the epithelial-mesenchymal transition during the progression of skin neoplasms; however, the expression of PADI2 in liver metastasis of CRC has not been reported." (PMID 29050308, 2017). "PADI2 has been shown to promote EMT during ovarian cancer progression and skin neoplasms." (PMID 37627159, 2023).
Autoimmunity (5 papers, 2013 to 2023). The occurrence of an immune reaction against the organism's own cells or tissues. "These previous studies suggest that PADI2 and its citrullination play an important role in RA autoimmunity." (PMID 24339914, 2013).
glioblastoma (5 papers, 2020 to 2023). The most malignant astrocytic tumor (WHO grade IV). "Peptidyl arginine deiminase, type II (PADI2), and UMP-CMP kinase (CMPK1) transcripts were similar between glioblastoma and normal brain tissues." (PMID 37762371, 2023).
lupus (5 papers, 2018 to 2024). "In TLR7-induced lupus, PADI2 and PADI4 promote the induction of TLR7 in lupus through innate and adaptive immunity." (PMID 37020554, 2023).
amyotrophic lateral sclerosis (4 papers, 2022 to 2024). Amyotrophic lateral sclerosis (ALS) is a neurodegenerative disease characterized by progressive muscular paralysis reflecting degeneration of motor neurons in the primary motor cortex, corticospinal tracts, brainstem and spinal cord. "For instance, FN1 and SIK3 are associated with spondyloepiphyseal dysplasia, PADI2 is related to sclerosis, ERBB4 is connected to amyotrophic lateral sclerosis (ALS), and B3GNT2 and BACE1 are associated with muscular dystrophy and muscular inflammation, respectively." (PMID 38788487, 2024).
breast tumors (4 papers, 2014 to 2025). "This study aimed to elucidate the tumorigenic role and regulatory pathway of PADI2 in breast tumors." (PMID 27478411, 2016). "PADI2 affects tumorigenesis in breast tumor cells by regulating the expression of ACSL4, BINC3 and CA9, which are known to promote abnormal lipid metabolism and cell invasion of tumors." (PMID 27478411, 2016). "In the present study, a significant decline in cell migration was detected in MCF-7 cells when PADI2 transcription was suppressed by siRNA, indicating that PADI2 expression contributes to abnormal migration of breast tumor cells." (PMID 27478411, 2016). "It is possible that both PADI2 and PADI4 are expressed in breast tumor tissues and function by different pathogenic pathways." (PMID 27478411, 2016). "The breast tumor cell line MCF-7 was treated with anti-PADI2 siRNA." (PMID 27478411, 2016). "PADI2 expression contributes to abnormal migration of breast tumor cells." (PMID 27478411, 2016). "PADI2 expression contributes to migration of breast tumor cells." (PMID 27478411, 2016). "Moreover, the study found that PADI2 can regulate ACSL4, BINC3 and CA9 expression to advance abnormal lipid metabolism and cell invasion in breast tumors." (PMID 27478411, 2016).
multiple myeloma (4 papers, 2017 to 2023). "In multiple myeloma, PADI2 is the most up-regulated transcript in bone marrow mesenchymal stem cells, which may mediate the up-regulation of IL-6 expression by inducing histone citrullination, enabling tumor cells to acquire resistance to anti-tumor drugs." (PMID 36479196, 2022). "In marrow, PADI2 and PADI3 were elevated in some SARS-CoV-2 biopsies, and interestingly PADI2 was found to be elevated in marrow mesenchymal stem cells, which upregulates IL-6 via histone H3 deimination in multiple myeloma, contributing to chemo-resistance." (PMID 32629995, 2020).
pneumonia (4 papers, 2021 to 2024). An acute, acute and chronic, or chronic inflammation focally or diffusely affecting the lung parenchyma, caused by an infection in one or both of the lungs (by bacteria, viruses, fungi, or mycoplasma.). "Moreover, a most recent study also showed that common introgression signals of alleles ADCY3, TRPV1, and PADI2 genes from wild relatives enhanced climatic adaptation and resistance to pneumonia in domestic sheep." (PMID 39725653, 2024).